ZEB1 (zinc finger E-box binding homeobox 1)
Diseases named in the same sentence as ZEB1 in open-access papers (continued):
Sharing a sentence is not in itself a finding about the gene and the disease.
cancer (continued). "In this study, we show a similar decrease in SNAI1, N-cadherin, and Zeb1 upon starvation-induced autophagy in two cancer cell lines." (PMID 30736337, 2019). "Previous studies have confirmed that Twist1, Snail1 and Zeb1 were the critical transcriptional factors regulating EMT of cancer cells." (PMID 30755243, 2019). "In fact, cancer cells with low expression of ESRP1/2 and high expression of ZEB1/2, are associated with aggressive behavior and poor prognosis, and express only the IIIc isoforms." (PMID 31682640, 2019). "As an important inducer driving EMT, hypoxia-induced ZEB1 modulated the interaction between cancer cells and TAMs, and this crosstalk, in turn, regulated ZEB1 expression itself." (PMID 31263103, 2019). "ZNF143 was shown to be a determinant of cancer cell motility, as it represses ZEB1, which results in upregulation of E-cadherin to maintain epithelial characteristics of proliferating cancer cells in response to IGF-1." (PMID 30885238, 2019). "During EMT and cancer metastasis, the levels of proteins such as N-cadherin, Zeb1, and vimentin significantly increase while the amount of E-cadherin decreases due to SNAI1-dependent transcriptional regulation." (PMID 30736337, 2019). "ZEB1 in hypoxic cancer cells promoted the migration of TAMs in vitro and altered the expression of multiple chemokines, especially CCL8." (PMID 31263103, 2019). "The expression of vimentin, Snail, and ZEB1 in cancer cells co-cultured with T-HESCs was examined by qPCR." (PMID 31040369, 2019). "Since ZEB1 is best known for driving EMT in cancer cells, we then tested its function in the cervical hypoxic TME and its correlation with TAM infiltration." (PMID 31263103, 2019). "ZEB1 function has been investigated in relation to radioresistance since ZEB1 is highly expressed in radioresistant-cancer cells." (PMID 31275381, 2019). "By screening for factors responsible for the stability of Zeb1 in cancer cells, we confirm that the downregulation of Siah1 and Fbxo45 mediates the RP11-induced stabilization of Zeb1 in CRC cells." (PMID 30979372, 2019). "A mesenchymal signature (VIM, FN1, LOX, GPC6, ZEB1) was defined as the highest co-correlated mesenchymal marker set in Cancer Cell Line Encyclopedia (CCLE) NSCLC cell lines." (PMID 31581742, 2019). "As ZEB1 was a master regulator of EMT process in many cancer types, we firstly considered to analyze the expression correlation of ZEB1 and IRF6 in GC." (PMID 31019894, 2019). "Despite being a transcription factor, ZEB1 can also be found in the cytoplasm of some cancer cells, probably reflecting that high levels of ZEB1 saturate the nuclear translocation system." (PMID 30910999, 2019). "It was reported that ZEB1 is abnormally expressed in various human cancers and commonly involved in cell migration, invasion and metastasis." (PMID 31007650, 2019). "For example, Hedgehog signaling, which is aberrantly activated in several types of cancers, linked Wnt signaling pathways with cell survival genes BCL2 and EMT driver genes SNAI1/2, ZEB1/2 through epigenetic or genetic alterations during carcinogenesis." (PMID 30548372, 2019). "Aberrant expression of several transcriptional repressors including Zeb1, Slug, and Twist induces E-cadherin downregulation at the invasive cancer front." (PMID 31934531, 2019). "Collectively, these results suggest RAE1 positively regulates ZEB1 expression during cancer progression." (PMID 30814639, 2019). "ASF1a interacts with the transcription factor β-catenin and activates the downstream genes cyclin D1, myc, Lgr5, and ZEB1, promoting cancer development and progression." (PMID 30692519, 2019).
cancer (continued). "On the basis of this and findings by others, we conclude that MA cells express a high ZEB1/low ESRP1/high CD44s network that enforces self-renewal in cancer stem–like cells." (PMID 31217902, 2019). "Previous studies have reported that histone H3K4 trimethylation within the ZEB1 promoter was involved in the regulation of ZEB1 in cancer cells." (PMID 30674889, 2019). "We find that EMT-related genes are highly correlated with intratumoral stromal cell abundance and identify a specific relationship between stroma-corrected ZEB1 expression and decreased immune activity in multiple cancer types." (PMID 31780722, 2019). "The accumulated evidence indicates that ZEB1 protein is predominantly present in the stromal compartment, but is largely absent in the epithelial compartment in several types of human cancers, including breast, pancreatic and colorectal cancers." (PMID 31324807, 2019). "At present, no studies have demonstrated the relationship between ADAMTS9-AS1 and ZEB1, or ADAMTS9-AS2 and ZEB1 or TMEM100 in cancer." (PMID 31827401, 2019). "In multivariate analysis, ZEB1 expression was an independent prognostic factor for cancer-specific survival (hazard ratio [HR], 0.367; p = 0.026)." (PMID 31655611, 2019). "The zinc finger e-box binding homeobox 1 (ZEB1) gene encodes a transcription factor involved in epithelial and endothelial cell plasticity critical in development, wound healing and cancer." (PMID 31194824, 2019). "As a first approach to identify putative ZEB1 kinases in cancer cells, we performed an in-silico screening of phosphorylation sites for multiple central kinases, including PKCs, PKA, MAPKs, and AKT." (PMID 31828042, 2019). "Using in vitro experiments and ex vivo cultures of human PCa slices, we demonstrated that LA and EPA exert anticancer effects, by modulating Ca2+ entry, which was involved in Zeb1 regulation and cancer cellular migration." (PMID 31752242, 2019). "We earlier found that Zeb-1 prevents various MCL cells against BTZ-induced apoptosis through cancer stem cell expansion and maintenance." (PMID 31022903, 2019). "Published studies have examined the potential value of ZEB-1 as a biomarker for the prognosis of cancer." (PMID 31248382, 2019). "Then, we observed that miR-101 target genes (c-Fos, ZEB1 and Mcl-1) known to promote cancer progression were significantly downregulated in AML cells with SNHG1 knockdown." (PMID 31615767, 2019). "To expand the repertoire of treatments for metastatic NSCLC, we utilized two independent screening approaches to identify ZEB1 interactors that are essential to cancer cell survival." (PMID 31719531, 2019). "NOTCH signaling pathway has been reported to play critical roles in the development and progression of human cancers through regulating ZEB1 expression and EMT pathway." (PMID 31019894, 2019). "Sirtuin 1 is involved in aging, and in numerous types of cancer, such as prostate cancer, where ZEB1 recruits SIRT1 to the E-cadherin promoter." (PMID 30791369, 2019). "A key regulator of EMT in cancer cells at the invasive front is the transcription factor ZEB1, which endows cancer cells with a pro-invasive and mesenchymal-like phenotype and predicts a worse clinical prognosis in most cancers." (PMID 31263103, 2019). "Zinc finger E-box binding homeobox 1 (ZEB1) is a molecule involved in the progression of epithelial-to-mesenchymal transition (EMT) in various kinds of cancers." (PMID 30976202, 2019). "Remarkably, we found that the invasion of PyMT-cancer cells was significantly inhibited in the presence of ZEB1-deleted CAFs (i.e., adeno-Cre-infected cells) compared with control CAFs (i.e., adeno-βGal-infected cells) at 18 and 24 h of culture." (PMID 31324807, 2019). "Although increased ZEB1 expression has largely been associated with EMT, cancer invasion, and tumorigenicity, there have been some episodic reports that have gone against the traditional reporting of the role of ZEB1." (PMID 32309604, 2018).
cancer (continued). "MYLK is responsible for the high proliferative ability of cancer cells through anti-apoptosis in which the p38 pathway is involved and represents a mediator of invasive behavior of cancer cells that are regulated by the ZEB1/miR-200 feedback loop." (PMID 29301256, 2018). "ZEB1 contributes to the resistance to anti‐cancer therapy by establishing a repressive chromatin state." (PMID 29744893, 2018). "Taken together, our data demonstrate that metformin inhibits TGF-β1-induced EMT-like process and cancer stem-like properties in GBM cells via AKT/mTOR/ZEB1 pathway and provide evidence of metformin for further clinical investigation targeted GBM." (PMID 29467947, 2018). "EMT is a process frequently associated with cancer and it involves multiple regulators, including SNAI1, SNAI2, TWIST1 and ZEB1 as well as their targets." (PMID 30379847, 2018). "This family of microRNAs has received much of the focus in regard to ZEB1 as studies in various cancer lines have shown that this family is the most upregulated when ZEB1 is knocked down." (PMID 32309604, 2018). "Based on our findings in cell culture, we suggest that ongoing repression of Zeb2 in the cancer cells allows the cells to respond to Tgf-β1 concentrated around airways and induce Zeb1 and EMT to facilitate invasion." (PMID 29930325, 2018). "The transcriptional inhibitor ZEB-1 is a well-known target of the miR-200 family members through a reciprocal repression mechanism to promote epithelial-mesenchymal transition and cancer invasion." (PMID 29720943, 2018). "GM-CSF-trained cancer cells displayed mesenchymal features, including motility and chemoresistance, and ZEB1 as well as MAPK/ERK signaling were identified as critical factors of GM-CSF-driven EMT." (PMID 30298120, 2018). "This work provides a resource for regulators of cancer progression that function under the transcriptional control of ZEB1." (PMID 29744893, 2018). "Zeb1 is a well-known EMT master regulator that induces mesenchymal properties in cancer cells by increasing N-cadherin and Vimentin levels making it more invasive and metastatic." (PMID 30483264, 2018). "Overall, the transcription factor ZEB1 mediates functions that link cancer EMT to TGFβ signaling, metastatic dissemination, stemness, and resistance to therapy." (PMID 29744893, 2018). "Zinc finger E‐box binding homeobox 1 (ZEB1) is a transcriptional regulator involved in embryonic development and cancer progression." (PMID 29744893, 2018). "We utilized a K-Ras-initiated model of lung AC12 to search for a CD44/Zeb1 loop in vivo, and address its potential role in cancer cell generation." (PMID 29930325, 2018). "NFATc1 is highly expressed in aggressive cancer cells and tissues, and promotes invasion through the transcriptional induction of Snail and Zeb1 in a TGF-β independent manner." (PMID 30534207, 2018). "Recent studies suggest an important role of EMT in resistance to gemcitabine, 5-FU, and cisplatin, which can be reversed by silencing of ZEB1 (Zinc finger E-box-binding homeobox 1) in resistant PDAC cancer cell lines." (PMID 30582059, 2018). "Twist-1, ZEB1/2, and Snail are all transcriptional repressors of E-cadherin and thus promote cancer cell EMT." (PMID 29435158, 2018). "A CD44/Zeb1 loop then initiates two-step transition of precancerous cells to cancer cells via a stable intermediate population of cancer-generating cells." (PMID 29930325, 2018). "Though Zeb1 has been widely studied in cancer biology, few evidences with immunity and inflammation make it a potential candidate to look upon for its role in cDCs trajectory." (PMID 30483264, 2018). "To further confirm the role of ZEB1 in aggressive cancer phenotypes, we ectopically overexpressed ZEB1 in LNCaP cells." (PMID 29754422, 2018). "Growing evidence indicates that the miR-200 family is involved in cancer cell migration via the targeting of ZEB1 and ZEB2." (PMID 29738527, 2018).
cancer (continued). "Even more curious than ZEB1 being described to have opposing functions, there has been opposing evidence with regard to its functions in cancer and cancer stem cell like characteristics." (PMID 30705664, 2018). "ZEB1 has been shown to upregulate or downregulate genes that play roles in cancer progression, invasion, migration, and metastasis." (PMID 32309604, 2018). "The role of Epithelial to Mesenchymal Transition (EMT) factor Zeb1 is well defined in metastasis and cancer progression but it's importance in dendritic cells (DCs) is unexplored until now." (PMID 30483264, 2018). "We found that samples displaying a high percentage of ZEB1-positive cells exhibited a high level of ATM expression, whereas cancers exhibiting lower ZEB1 levels showed diminished ATM expression." (PMID 29352223, 2018). "The percent of lineage‐traced cancer cells expressing Zeb1 or Fsp1 in the primary tumors were similar to the previously reported findings." (PMID 30120146, 2018). "Nevertheless, our current finding demonstrated that ZEB1 played a role in regulating VM formation in PCa vivo and in vitro and provided an explanation for ZEB1 promotion in cancer progression." (PMID 29754422, 2018). "HMGB1 inhibition in the feeder supernatant significantly decreased the up-regulation effect of Zeb1 and Slug on cancer cells." (PMID 29615080, 2018). "In rescue experiments, cancer cells with stable ectopic OGN expression were transiently transfected with Zeb-1, Slug or Snail." (PMID 29499765, 2018). "Conversely, activation of OCT4 signaling and upregulation of EMT inducer ZEB1 induce PD-L1 expression in cancer cells, thereby suggesting a possible immune evasion mechanism employed by cancer stem cells during metastasis." (PMID 30283733, 2018). "It is known that ZEB1 promotes cancer progression through a variety of genetic and epigenetic mechanisms." (PMID 29352223, 2018). "Overexpression of ZEB1 and ZEB2 is a common phenomenon in many types of cancer, where it is associated with the maintenance of a cancer stem cell phenotype as well as metastasis and therapy resistance, such as paclitaxel resistance in breast cancer cells." (PMID 29164272, 2018). "For example, CDH1 and polarity genes (Crumbs3, Lgl2) are known direct target genes repressed by ZEB1 in carcinoma EMT." (PMID 29744893, 2018). "This generates a strong interest in deciphering the complete regulatory network downstream of ZEB1 in carcinomas." (PMID 29744893, 2018). "Given the pivotal role of ZEB1 in downregulating CDH1 and inducing the loss of cell polarity, ZEB1 drives the EMT and cancer progression." (PMID 28088787, 2017). "Consistently, the migration and invasion of GM-CSF-educated cancer cells decreased when ZEB1 was knockdown." (PMID 28811578, 2017). "Collectively, these findings showed that POU2F1 induced the transcription of Twist1, Snai1, Snai2 and ZEB1 genes which induce cancer cell EMT." (PMID 28489585, 2017). "For examples, oncogenic KRAS regulated miR-200c, while miR-200c targeted ZEB1/ZEB2 (ZEB1/ZEB2 functions as an oncogene to promote the cancer metastasis)." (PMID 28736730, 2017). "ZEB1 and HAS2 expression strongly correlates in various cancer entities and high HAS2 levels associate with an early relapse." (PMID 28086235, 2017). "We also examined the relationship between ZEB1 and IL‐6 in other types of cancers using a tissue array of 448 cancer tissues from multiple organs and found other double‐positive cancers." (PMID 28618162, 2017). "This process represents a switch in cell differentiation and behaviour that contributes to cancer progression, and is mediated by key transcription factors, including Snail, Slug and ZEB1." (PMID 28977999, 2017). "ZEB1, a member of the zinc-finger E-box binding homeobox family, is considered to play a crucial role in cancer progression and metastasis." (PMID 29245917, 2017).
cancer (continued). "The neurogenin 3 gene (Ngn3) is a bona fide target of ZEB1, and its repression is a key factor contributing to ZEB1-induced cancer cell stemness." (PMID 28903350, 2017). "Apart from its EMT-modulatory role, ZEB1 has been reported to enhance cell proliferation in several cancers and miR-150-5p acted as a growth suppresser." (PMID 28697764, 2017). "The experiment by Zhu Zusen group proved that NRARP knockout led to attenuate cancer cell stemness which is linked with EMT by TWIST1 and ZEB1, two EMT related transcription factors that are also highly correlated with NRARP." (PMID 28207739, 2017). "Especially, the miR-200 family (miR-200a, miR-200b, miR-200c, miR-141, and miR-429) appears to exert an inhibitory effect on EMT in a number of cancers by repressing transcription factors zinc finger E-box binding homeobox 1 (ZEB1) and 2 (ZEB2)." (PMID 28552992, 2017). "Then, the expression levels of genes zeb1 and cdh1 and the probabilities of an individual cancer cell appearing in three phenotypic states are compared with those of the human breast SUM159 line." (PMID 28852133, 2017). "To investigate the mechanism by which these miRNAs induced an MET phenotype, we evaluated the EMT marker genes E-cadherin, Vimentin, ZO-1, ZEB1 and Snail in several cancer cell lines, Panc1, KP4-4, SU.86.86, BxPC3 and MDA-MB-231." (PMID 28638102, 2017). "A recent report suggested that inflammation induces disseminated, dormant cancer cells to form metastatic tumors through functions of ZEB1." (PMID 28618162, 2017). "We also examined the involvement of Ngn3 in ZEB1-regulated cancer cell stemness properties in SUM-159 cells, with similar results." (PMID 28903350, 2017). "Meanwhile, some EMT key regulatory factors, such as Zeb1, Twist, Snail and Slug, which participate in cancer progression or cancer metastasis, are also involved in TGF-β1-induced EMT." (PMID 28978036, 2017). "In contrast, ZEB1 depletion achieved the opposite effect, i.e. reduced cancer stem-like cell properties." (PMID 28903350, 2017). "POU2F1 induced the transcription of Twist1, Snai1, Snai2 and ZEB1 genes which induce cancer cell EMT." (PMID 28489585, 2017). "As an important EMT regulator, the aberrant expression of ZEB1 was also found in VM forming cancer cell lines." (PMID 28938545, 2017). "Taken together, these results suggested that ZEB1 expressed in cancer cells contributes to the growth of fibroblasts in paracrine and context‐dependent manners." (PMID 28618162, 2017). "Our data elucidates an important role for ZEB1/Ngn3 signaling in regulating stem cell fate and suggests a potential therapeutic target for ZEB1-overexpressing cancers." (PMID 28903350, 2017). "In cancer cells, miR-200 s induce epithelial differentiation by suppressing ZEB1/2 and subsequently increasing E-cadherin expression." (PMID 28637482, 2017). "ZEB1 expression seems to be regulated by MAPK/ERK signals, because knockdown of ERK1 or 2 decreased ZEB1 expression in GM-CSF-stimulated cancer cells." (PMID 28811578, 2017). "Although ZEB1 protein is present in the majority of carcinoma cell lines exhibiting mesenchymal properties, expression of ZEB2 is uncommon." (PMID 28783176, 2017). "Through driving epithelial-mesenchymal transition (EMT), ZEB1 contributes to the metastasis of carcinoma cells, and prior studies demonstrated that ZEB1 conferred stemness and resistance." (PMID 29245917, 2017). "In several cases, the immunoexpressions of ZEB1 were identified in the stroma as well as carcinoma tissues." (PMID 29245917, 2017). "In analogy to the well-established concept of ZEB1 as a marker of disease progression in carcinomas, we performed survival analysis separating the dataset into tumors with low versus high ZEB1 labelling index." (PMID 28945795, 2017). "The only exception was ZEB1 which was at similar levels in the cancer cells and in the stroma in the MDA-MB-231 tumors." (PMID 27809802, 2016).